DENND1B (DENN domain containing 1B)
Description:
Guanine nucleotide exchange factor (GEF) for RAB35 that acts as a regulator of T-cell receptor (TCR) internalization in TH2 cells. Acts by promoting the exchange of GDP to GTP, converting inactive GDP-bound RAB35 into its active GTP-bound form. Plays a role in clathrin-mediated endocytosis. Controls cytokine production in TH2 lymphocytes by controlling the rate of TCR internalization and routing to endosomes: acts by mediating clathrin-mediated endocytosis of TCR via its interaction with the adapter protein complex 2 (AP-2) and GEF activity. Dysregulation leads to impaired TCR down-modulation and recycling, affecting cytokine production in TH2 cells.
Synonyms: C1orf218; FAM31B; MGC27044; FLJ20054; C1ORF18
Tractability: PROTAC: ubiquitination databases record sites on it.
Gene: Protein-coding gene on chromosome 1 (197,504,748 to 197,775,706, reverse strand). Ensembl gene ENSG00000213047.
Subcellular location: Cytoplasm, cytosol; Cytoplasmic vesicle, clathrin-coated vesicle
Subcellular location (Human Protein Atlas): Cytosol; Nuclear speckles
Pathways (Reactome):
Vesicle-mediated transport: RAB GEFs exchange GTP for GDP on RABs
Gene Ontology:
Molecular function: guanyl-nucleotide exchange factor activity; phosphatidylinositol phosphate binding; small GTPase binding
Biological process: positive regulation of T-helper 2 cell cytokine production; T cell receptor signaling pathway; endocytic recycling; endocytosis; regulation of immune response
Cellular component: cytosol; clathrin-coated vesicle
Genetic constraint (gnomAD): Loss-of-function variants: 30 observed, 50.97 expected, observed/expected ratio (o/e) 0.59, 90% interval 0.44 to 0.8. The upper end of that interval is the gene's LOEUF score, 0.8, which puts it in group 3 of 6, group 1 being the genes least tolerant of losing a copy. Missense variants: 661 observed, 744.14 expected, observed/expected ratio (o/e) 0.89, 90% interval 0.83 to 0.95. Synonymous variants: 270 observed, 279.19 expected, observed/expected ratio (o/e) 0.97, 90% interval 0.88 to 1.07.
Homologues: Orthologues: chimpanzee DENND1B (99% identical), macaque DENND1B (98% identical), rabbit DENND1B (89% identical), dog DENND1B (86% identical), guinea pig DENND1B (86% identical), mouse Dennd1b (84% identical), rat Dennd1b (83% identical), pig DENND1B (77% identical), tropical clawed frog dennd1b (61% identical), Drosophila melanogaster CG18659 (28% identical), zebrafish dennd1b (27% identical), Caenorhabditis elegans rme-4 (24% identical). Paralogues in human: DENND1A (46% identical), DENND1C (39% identical).
Diseases named in the same sentence as DENND1B in open-access papers:
DENND1B is named in the same sentence as 21 diseases in open-access papers, as found by Europe PMC text mining. Sharing a sentence is not in itself a finding about the gene and the disease. The quoted sentences say what the papers report.
asthma (20 papers, 2010 to 2025). "IBD and asthma also share susceptibility genes, including gene loci DENND1B, SMAD3, SLC22A4/5 (5q31/IBD5) and ORMDL3 gene variants." (PMID 37835065, 2023). "Among these were DENND1B which is involved in the down-modulation of the T cell receptor, and its absence, malfunction or delay has been associated with asthma and allergic response." (PMID 34136502, 2021). "These include loci associated with asthma in other populations such as the DENND1B gene, located on chromosome 1q31." (PMID 27990118, 2016). "Subsequent GWA studies of asthma identified variants in PDE4D and DENND1B associated with asthma at genome-wide significant levels, although the proposed variant in DENND1B showed considerable heterogeneity of associations between different populations." (PMID 23028483, 2012). "Furthermore, a DENND1B SNP in human, causing reduced expression of its protein, is associated with asthma." (PMID 29734372, 2018). "In particular, we identified strong environmental interactions with asthma risk SNPs near the DENND1B and RORA genes and strong environmental interactions with alopecia areata, Crohn’s disease, membranous neuropathy, neuroblastoma, and systemic lupus erythematosus in several immune system genes." (PMID 26170196, 2015). "Furthermore, a recent genome-wide association study (GWAS) identified DENND1B as an asthma susceptibility gene in children, with evidence suggesting that certain variants of DENND1B may also be linked to BMI in children with asthma." (PMID 40426941, 2025). "Functional gastrointestinal disorders (FGID) studies have shown that genes related to asthma, such as DENND1B, SMAD3, SLC22A4/5 (5q31/IBD5), and ORMDL3, have been co-associated with Crohn's disease and ulcerative colitis." (PMID 37656879, 2023). "Distinct genetic loci, including mothers against decapentaplegic homolog 3 (SMAD3), DENN domain containing 1B (DENND1B), and Solute carrier family 22, member 4/5 [SLC22A4/5 (5q31/IBD5)], are known to be associated with both CD and asthma." (PMID 32181078, 2020). "The contribution of other known atopy variants, such as those in the DENND1B gene, located on chromosome 1q31 and the ORMDL3 gene, located on chromosome 17q12 to the asthma phenotype is also possible." (PMID 27990118, 2016). "Additionally, detrimental off-targeting to DENND1B can result in a defective TCR internalization machinery, causing abnormal T-cell effector functions like asthma." (PMID 41404500, 2025). "Moreover, an association with both asthma and Crohn’s disease was found for gene loci DENND1B, SMAD3 and SLC22A4/5 (5q31/IBD5), while the ORMDL3 gene variants present in Crohn’s disease and ulcerative colitis were also associated with childhood-onset asthma." (PMID 37835065, 2023). "Furthermore, we found no deletions or duplications nominally associated with asthma symptoms in loci consistently associated with the disease in previous studies, including: DENND1B, IL1RL1, PDE4D, TSLP, IL13, HLA-DR/DQ and IL33 regions." (PMID 30262839, 2018). "A good example is provided by the DENND1B protein (UniProtKB Q6P3S1): an article reporting that variations in the DENND1B protein-coding gene are associated with susceptibility to asthma was not curated 4 years ago, because we considered that insufficient evidence was available at that time." (PMID 29036270, 2017). "Genome-wide association (GWA) studies on asthma have suggested that several polymorphisms in several genes, including ORMDL3-GSDMB, DENND1B, HLA-DP, SLC30A8, IL1RL1-IL18R1, IL33, SMAD3, TSLP, and NOTCH4 are associated with asthma." (PMID 23861779, 2013).
childhood asthma (4 papers, 2011 to 2022). "The gene DENND1B encodes the guanine nucleotide exchange factor (GEF) for RAB35 that acts as a regulator of T-cell receptor (TCR) internalization in TH2 cells which functions as a regulator in the process of childhood asthma." (PMID 35198010, 2022). "The novel loci included SNPs in or near the DENND1B (DENN domain containing 1B) gene, which has been implicated in childhood asthma; RNF103 (ring finger protein 103), a suspected antidepressant target and genes related to axon guidance (DCC netrin 1 receptor)." (PMID 31576797, 2020). "The DENND1B locus has previously been associated with IBD (rs2488389), PBC (rs2488393) and childhood asthma (rs2786098; refs 25, 26, 38)." (PMID 25651891, 2015).
inflammatory bowel disease (3 papers, 2020 to 2021). A spectrum of small and large bowel inflammatory diseases of unknown etiology. "We observed substantial polygenic overlap between MSA and inflammatory bowel disease and identified 3 shared genetic loci with leading variants upstream of the DENND1B and RSP04 genes, and in intron of the C7 gene." (PMID 33107653, 2021).
clear cell renal cell carcinoma (2 papers, 2022 to 2025). "For example, a circular RNA form of DENND1B (circ_DENND1B) was found to inhibit tumorigenicity in clear cell renal cell carcinoma (ccRCC)." (PMID 40535770, 2025).
depression (2 papers, 2021 to 2022). "DENND1A SNPs are associated with depression, and the DENND1B transcript is downregulated in patients with depression." (PMID 35280519, 2021).
Obesity (2 papers, 2013 to 2025). Accumulation of substantial excess body fat. "The rest of the candidates, C2orf15, DENND1B, MRPL30, POC1B, RP4-655J12.3, TMBIM4, BMP2 K, CSRNP2, NCKAP5L, TOMM5, and BAP1, may be novel genes related to T2DM or obesity." (PMID 24455749, 2013).
psoriasis (2 papers, 2015 to 2016). An autoimmune condition characterized by red, well-delineated plaques with silvery scales that are usually on the extensor surfaces and scalp. "A novel psoriasis risk variant (rs2477077) mapping to DENND1B was also found to be associated with psoriasis per se." (PMID 26255310, 2016). "The results suggest that DENND1B is a susceptibility locus for psoriasis per se." (PMID 25651891, 2015). "The function of DENND1B is not fully understood, but it has been found to be upregulated in T cells providing support for the relevance of this type of cell in PsA and psoriasis aetiology." (PMID 25651891, 2015).
autoimmune disease (1 paper, 2023). A disorder resulting from loss of function or tissue destruction of an organ or multiple organs, arising from humoral or cellular immune responses of the individual to their own tissue constituents. "Almost all variants identified (ZNF365, TNFSF4, NAB1, IKZF4-ERBB3, CTSC, DENND1B, SIRPG, and PRF1) are the same or strongly linked with markers associated with other autoimmune diseases." (PMID 37188663, 2023).
autoimmune liver disease (1 paper, 2025). "Previously, DENND1B was associated with autoimmune liver disease in genome-wide meta-analyses." (PMID 40535770, 2025).
gastric cancer (1 paper, 2025). A primary or metastatic malignant neoplasm involving the stomach. "Furthermore, a few SNPs in DENND1B have been reported to increase the risks of pancreatic, renal and gastric cancers." (PMID 40535770, 2025).
tumor (2 papers, 2022 to 2025). "circ_DENND1B overexpression inhibited the tumor growth of ccRCC in vivo." (PMID 36578555, 2022).
DENND1B also shares sentences with these, for which no sentence is quoted: Crohn disease (3 papers); allergic response (2); ulcerative colitis (2); Allergy (1); alopecia areata (1); atopic dermatitis (1); immune diseases (1); neuroblastoma (1); pancreas cancer (1); systemic lupus erythematosus (1).